RGS4 (regulator of G protein signaling 4)
Diseases named in the same sentence as RGS4 in open-access papers (continued):
Sharing a sentence is not in itself a finding about the gene and the disease.
cardiac hypertrophy (7 papers, 2012 to 2023). "RGS4 was also upregulated in experimental rats of cardiac hypertrophy, including primary cardiomyocytes in culture in vitro and pulmonary artery-banded mice in vivo." (PMID 37047106, 2023). "Exogenous overexpression of RGS4 in cardiomyocytes attenuates endothelin receptor signaling, reducing PLCβ activation, contractility in the long term, and cardiac hypertrophy." (PMID 36547076, 2022). "In PlGF/RGS4 mice, the angiogenesis-induced hypertrophic response was completely prevented compared with PlGF mice and the extent of myocardial hypertrophy and the decline in cardiac function after TAC were each comparable with control." (PMID 26888314, 2016). "To further investigate the role of miR-182 in angiogenesis-induced cardiac hypertrophy, we determined its expression in the PlGF/RGS4 mouse, where induced cardiac expression of RGS4 concurrently with PlGF inhibits the hypertrophic response." (PMID 26888314, 2016). "Indeed, RGS4 ameliorates cardiac hypertrophy induced by pressure overload via direct inhibition of the Gq protein-dependent pro-hypertrophic signaling in murine hearts." (PMID 35628613, 2022). "Consequently, the expression of miR-182 and myocardial hypertrophy were inhibited by the concomitant transgenic expression of PlGF and RGS4, or the expression of PlGF in eNOS−/− mice." (PMID 26888314, 2016). "In anti-myocardial hypertrophy, regulators of G-protein signaling (RGS), namely, RGS2 and RGS4, have a central role, leading to cGMP-mediated anti-myocardial hypertrophic effects by inactivating G-protein-coupled signaling, as RGS2 and RGS4 are targets of PKG." (PMID 38186653, 2023). "Exogenous overexpression of RGS4 in cardiomyocytes attenuates endothelin receptor signaling, reducing phospholipase C (PLC)-β activation, contractility in the long term, and cardiac hypertrophy." (PMID 35628613, 2022). "Increased capillary activity leads to massive release of nitric oxide (NO) which results in the degradation of regulator of G-protein signaling 4 (RGS4), thus activating G protein-coupled receptor (GPCR) mediated downstream signaling pathways such as PI3K and mTOR to promote cardiac hypertrophy." (PMID 33178704, 2020).
glioblastoma (7 papers, 2009 to 2024). The most malignant astrocytic tumor (WHO grade IV). "Studies have shown that overexpression of RGS4 is associated with the development and poor prognosis of glioblastoma and non-small cell lung cancer." (PMID 38693916, 2024). "RGS4 has recently been studied as a tumor promoter in glioblastoma, non-small cell lung cancer and osteosarcoma tumors, and is reported to be a potent driver of cell proliferation, invasion and migration." (PMID 38693916, 2024). "RGS4 was identified as having a cell growth suppression function in glioblastoma, thyroid, and ovarian cancers." (PMID 36430806, 2022). "RGS4 was found to overexpress in glioblastoma, and its knockout reduces GSC migration, invasion, and induces apoptosis in tumor cells, suggesting its risk role in cancer patients like our findings." (PMID 33889544, 2021). "To better understand the effect and role of RGS4 in glioblastoma prognosis, we opted for a data mining approach." (PMID 32392739, 2020). "Our studies demonstrate that RGS4 is highly expressed in clinical specimens of glioblastoma substantiated by the TCGA data." (PMID 32392739, 2020). "Similarly, RGS4 has been reported to be a key driver of glioblastoma invasiveness." (PMID 27105500, 2016). "Using the data obtained from the TCGA GBM cohort and glioblastoma biodiscovery portal, we plotted the overall survival by dichotomizing all the patients into two groups, based on the median of RGS4 gene expression, both low and high." (PMID 32392739, 2020). "To investigate if RGS4 could be a potential predictor for GBM tumor growth and progression, we performed immunohistochemical analysis on five human glioblastoma (hGBM) patient biopsy tissues, and the positive staining results revealed significantly increased RGS4 expression." (PMID 32392739, 2020). "As expected, VEGF was strongly overexpressed in glioblastoma samples, whereas RGS4 (regulator of G-protein signaling 4), a negative regulator of VEGF-signaling, was downregulated." (PMID 19924294, 2009). "Here, we hypothesize that glioblastoma (GBM) tumors rely on GPCR regulation, making RGS4 an excellent candidate as a tumor-promoting gene." (PMID 32392739, 2020).
neuroblastoma (7 papers, 2012 to 2023). Neuroblastoma (NB) is the most common solid, extracranial childhood tumor. "Common targets for both HIFs include vascular endothelial growth factor (VEGFA) and RGS4 gene coding for a protein regulating signaling activity of G-proteins, which enhanced expression is specific for hypoxic neuroblastoma cells." (PMID 32722310, 2020). "In the human neuroblastoma cell lines, Rgs4 is responsive to hypoxia in a similar timeframe to other direct targets of HIF transactivation, and a dissimilar timeframe to indirect HIF-responsive genes." (PMID 22970249, 2012). "Together these data demonstrate the cell-specific induction of Rgs4 by hypoxia in pheochromocytoma and neuroblastoma cells, and are consistent with a role of the HIF pathway in this response." (PMID 22970249, 2012). "We report gene expression analysis demonstrating that Rgs4 is a cell-type specific hypoxia inducible target in PC-12 and neuroblastoma cell lines, under the control of HIF-1 and HIF-2." (PMID 22970249, 2012). "Notably, these responses of Rgs4 have only been seen in sympathetic cancer cell types such as neuroblastoma and pheochromocytoma, while previously characterised HIF target genes are regulated by hypoxia in a wider array of cell types, such as HUVECs." (PMID 22970249, 2012). "Wang and colleagues conducted the research at the cellular level, and measured RGS4 expression in human neuroblastoma SH‐SY5Y cells; however, our study is at the animal level and we measured RGS4 expression in NAc core of rats." (PMID 36793204, 2023). "Whilst we demonstrate here that Rgs4 is induced by hypoxia via a HIF-mediated mechanism in specific cell types, it is likely that a detailed ChIP-Seq approach for HIF-1 and HIF-2 using neuroblastoma cells will be required to definitively identify the DNA binding site for HIF." (PMID 22970249, 2012). "In neuroblastoma cells expressing endogenously RGS4 and MOR, knockdown of RGS4 does not affect the action of morphine on MOR, suggesting that the ability of RGS4 to regulate MOR may be determined by the cell type and/or agonist." (PMID 37089428, 2023). "In contrast, in SH-SY5Y human neuroblastoma cells that endogenously express RGS4 and MOR, knockdown of RGS4 did not affect responses to the MOR agonist morphine, suggesting that the ability of RGS4 to regulate MOR may be determined by the cell type and/or the agonist." (PMID 32038168, 2020).
atrial fibrillation (6 papers, 2013 to 2023). A disorder characterized by an electrocardiographic finding of a supraventricular arrhythmia characterized by the replacement of consistent P waves by rapid oscillations or fibrillatory waves that vary in size, shape and timing and are accompanied by an irregular ventricular response. "RGS4 absence results in a predisposition to atrial fibrillation through the IP3-Ca2+ release way." (PMID 36187006, 2022). "The regulator of G-protein Signaling (RGS)-4 inactivates (terminates) both Gi/o- and Gq-protein signaling and, in the heart, protects against atrial fibrillation via calcium signaling attenuation." (PMID 35628613, 2022). "Moreover, RGS4 protects against abnormal calcium transients and signaling that can lead to tachyarrhythmias and atrial fibrillation (AFib)." (PMID 35628613, 2022). "Absence of RGS4 gene induces atrial fibrillation and its activation leads to cardioprotective effects due to increased expression of natriuretic peptides in the heart." (PMID 35413811, 2022).
heart failure (6 papers, 2012 to 2025). Inability of the heart to pump blood at an adequate rate to meet tissue metabolic requirements. "This provides another line of evidence for the cardioprotective role of RGS4 against inflammation and fibrosis, two maladaptive processes of the heart known to lead to AFib, arrhythmias, and heart failure." (PMID 36547076, 2022). "Others reported that increases in cardiac muscle expression of RGS4 decreases cardiac inotropy that promotes heart failure." (PMID 22253691, 2012). "In addition, three target genes (ITIH5, NRK, PDE5A) in DCM and RGS4 in heart failure have been reported to be up-regulated, the expression trend of these genes is consistent with our analysis results." (PMID 37268658, 2023). "Therefore, systemic RGS4 pharmacological stimulation might be of therapeutic value in heart disease, particularly in chronic human heart failure and in systemic hypertension." (PMID 35628613, 2022). "Cardiac, as well as neuronal, RGS4 stimulation might, thus, be advantageous in helping the failing heart cope with the toxic effects, both direct and indirect (via sympathetic hyperactivation), of SCFAs that are aberrantly upregulated in human heart failure." (PMID 35628613, 2022). "Since RGS4 expression is upregulated in failing human hearts, and overexpression of RGS4 impairs cardiac myocyte contractility and increases heart failure in a mouse model, we next examined whether mitogens attenuate agonist-induced contractile responses in an RGS4-dependent manner." (PMID 22253691, 2012).
depression (5 papers, 2014 to 2023). "Blocking of RGS4 using CCG55014 did not change the respiratory depression induced by MOR activation despite co-expression of RGS4 and MORs in the brainstem." (PMID 37089428, 2023). "As related to depression, the RGS family members, RGS2, RGS4, RGS6 and RGS8 have all surfaced as being involved with regulating the manifestation of depression or play role as antidepressants through their capacity to activate different downstream molecular mechanisms." (PMID 34674723, 2021).
melanoma (5 papers, 2017 to 2023). A malignant, usually aggressive tumor composed of atypical, neoplastic melanocytes. "Meanwhile, by analyzing the associations with clinicopathological characteristics of melanoma, we found that RGS4 expression was significantly correlated with TNM stage (P < 0.01)." (PMID 29108247, 2017). "Tissue microarray of 48 cases of sample, containing 8 cases of melanocytic nevus tissue and 40 cases of melanoma tissue, was immunohistochemically stained for RGS4 protein." (PMID 29108247, 2017). "For the first time, our studies found that the expression of RGS4 in melanoma tissues was lower than that of melanocyte nevus tissues." (PMID 29108247, 2017). "RGS4-high expression rate (75%,6/8) in melanocytic nevus tissues was obviously higher than the rate (27.5%,11/40) in melanoma tissues (P < 0.05)." (PMID 29108247, 2017). "In this research, we found overexpression of RGS4 restrained melanoma cell migration and invasion; also decreased the expression of MMPs." (PMID 29108247, 2017). "Here we identified regulator of G protein signaling 4(RGS4) as novel therapeutic target for malignant melanoma and its regulating effect on melanoma." (PMID 29108247, 2017). "To elucidate the molecular mechanism of the inhibition of melanoma cell invasion and migration under high level of RGS4, we detected the effect of RGS4 on the expression of matrix metalloproteinases (MMPs), the crucial molecules in cell invasion." (PMID 29108247, 2017). "As expected, up-regulation of E-cadherin was observed in RGS4 overexpression A375 cell, demonstrating that overexpression of RGS4 inhibits melanoma cell migration and invasion." (PMID 29108247, 2017). "Our studies indirectly confirmed that RGS4 inhibited cell migration and invasion in melanoma by depressing the expression of EMT-related markers." (PMID 29108247, 2017). "To investigate the biological functions of RGS4 in melanoma development, we selected A375 cell, with endogenous low RGS4 expression, to be transfected with pcDNA3.1-RGS4." (PMID 29108247, 2017). "Collectively, our findings show that RGS4 plays an important role in multiple cellular functions of melanoma development and is valuable to be a therapeutic target." (PMID 29108247, 2017). "To further confirm the effect of knockdown of RGS4 on melanoma, we selected M14 cell line for cell function assays." (PMID 29108247, 2017). "There were strong immunohistochemistry staining of RGS4 in melanocytic nevus tissue while it significantly decreased in melanoma tissue." (PMID 29108247, 2017). "And knockdown of RGS4 activated melanoma cell migration and invasion; also degradation of RGS4 increased the expression of MMPs." (PMID 29108247, 2017). "In our study, we found that overexpression of RGS4 inhibited melanoma cell proliferation and promoted apoptosis in melanoma cells." (PMID 29108247, 2017). "Additionally, RGS4 has been reported as a potential therapeutic target for suppressing proliferation and invasion of A375 melanoma cells." (PMID 36430806, 2022). "In addition, treatment of LY294002 on the cells blocked activation of PI3K/AKT, Cyclin D1 and E2F1 due to the knockdown of RGS4 in melanoma cells and consequently decreased the expression of p-Akt, Cyclin D1 and E2F1." (PMID 29108247, 2017). "We found that endogenous RGS4 expression was much lower in melanoma tissues and cells." (PMID 29108247, 2017). "In conclusion, for the first time we found that RGS4 expression was downregulated in melanoma tissues and cells which inhibited melanoma cell proliferation, migration and invasion due to the inactivation of Cyclin D1 and E2F1 via GPCR-mediated PI3K/AKT pathway." (PMID 29108247, 2017). "Our results showed that RGS4 could significantly reduce the proliferation, migration and invasion of melanoma cells." (PMID 29108247, 2017). "Our results showed that RGS4 expression level was much lower in melanoma cells than in HEM cells." (PMID 29108247, 2017).
melanoma (continued). "CCK8 and colony formation assay were performed to evaluate whether the reduction of RGS4 may affect the proliferation of melanoma cell." (PMID 29108247, 2017). "Therefore, we hypothesized that RGS4 directly induced inactivation of E2F1 under the regulation of Cyclin D1 or AKT in melanoma." (PMID 29108247, 2017). "However, the physiological function of RGS4 in malignant melanoma is not well known so far." (PMID 29108247, 2017). "Furthermore, downregulation of RGS4 facilitates melanoma cell migration and invasion." (PMID 29108247, 2017). "Our findings suggest that RGS4 might be a new therapeutic target for malignant melanoma." (PMID 29108247, 2017). "In this study, our results supported the hypothesis that RGS4 led to downregulation of Cyclin D1 and E2F1 expression via inactivation of the GPCR-mediated PI3K/AKT pathway, and as the results, inhibited melanoma cell growth, proliferation and so on." (PMID 29108247, 2017). "Therefore, we can say that RGS4 inhibits Cyclin D1 via PI3k/AKT signaling pathway for proliferation, migration of melanoma cells." (PMID 29108247, 2017).
non-small cell lung carcinoma (5 papers, 2021 to 2024). A group of at least three distinct histological types of lung cancer, including non-small cell squamous cell carcinoma, adenocarcinoma, and large cell carcinoma. "In human non-small cell lung cancer (NSCLC), RGS4 has been identified as a novel tumor suppressor with prognostic potential." (PMID 36430806, 2022).
Airway obstruction (4 papers, 2012 to 2021). Obstruction of conducting airways of the lung. "Increase of RGS4 in human bronchial smooth muscle cells caused severe airway obstruction and RGS4-/- mice exhibited diminished allergen-induced AHR through the increased secretion of the bronchodilator PGE2." (PMID 34502263, 2021). "Given the necessity of RGS4 in regulating ASM proliferation, we posited that patients with severe asthma, who manifested marked increases in bronchial smooth muscle mass and irreversible airway obstruction, would manifest increased numbers of RGS4+ ASM cells." (PMID 22253691, 2012). "The selective induction of RGS4 by HASM mitogens suggested a potential function in the ASM hyperplasia and fixed airway obstruction associated with severe asthma." (PMID 22253691, 2012). "Moreover, RGS4 (also negatively correlated with miR-26a-5p) plays a role in modulating airway hyper-responsiveness and airway obstruction." (PMID 32998415, 2020). "Further, RGS4 expression in ASM cells is associated with increasing disease severity and may serve as a unique biomarker and/or therapeutic target to abrogate ASM hyperplasia and irreversible airway obstruction in asthma." (PMID 22253691, 2012). "RGS4 was required for ASM hyperplasia and rendered cells poorly contractile, a feature characteristic of more severe, irreversible airway obstruction." (PMID 25041788, 2014). "Therapeutic approaches that decrease RGS4 expression or antagonize RGS4 function may prevent ASM hyperplasia and irreversible airway obstruction while promoting a more responsive smooth muscle phenotype." (PMID 22253691, 2012).
gastric cancer (4 papers, 2007 to 2024). A primary or metastatic malignant neoplasm involving the stomach. "Considering that RGS4 is associated with poor prognosis in four gastric cancer data sets, we then focused on exploring the effect of RGS4 on the prognosis and treatment of gastric cancer." (PMID 38693916, 2024). "We further analyzed the effect of RGS4 on prognosis in all gastric cancer cohorts." (PMID 38693916, 2024). "In addition, we investigated the function of RGS gene family, especially RGS4, in regulating gastric cancer formation and tumor microenvironment." (PMID 38693916, 2024). "An immunohistochemical (IHC) investigation assessed the expression levels of hub genes (SDC2, RGS4, SERPINE1, DUSP1, and CAV1) in gastric cancer." (PMID 39871942, 2024). "For example, patients with high expression of RGS4 and TXNIP exhibited a poorer prognosis in gastric cancer, while those with high expression of SLC1A5 have a better prognosis within five years." (PMID 36418919, 2022). "Our work comprehensively explored important role of RGS gene family in gastric cancer for the first time and speculated that the RGS gene family, particularly RGS4, could be a prognostic and therapeutic target for gastric cancer." (PMID 38693916, 2024).
ovarian carcinoma (4 papers, 2016 to 2024). A malignant neoplasm originating from the surface ovarian epithelium. "RGS4 was previously found to be down-regulated in invasive cancers compared to either non-invasive cancer or normal epithelial cells for both breast and ovarian cancer systems." (PMID 27600078, 2016). "This five-gene signature (RGS11, RGS10, RGS13, RGS4, and RGS3) is overexpressed in ovarian cancer and involved in extracellular matrix–receptor interaction, the TGF-β signaling pathway, the Wnt signaling pathway, and the chemokine signaling pathway." (PMID 39145770, 2024).
Parkinson disease (4 papers, 2015 to 2022). A progressive degenerative disorder of the central nervous system characterized by loss of dopamine producing neurons in the substantia nigra and the presence of Lewy bodies in the substantia nigra and locus coeruleus. "It was found that inhibition of RGS4 was observed to reinstate ECB-LTD in the presence of a D2-antagonist (sulpiride), while RGS4 deficient 6-OHDA denervated mice were resistant to some features of motor dysfunction typical of parkinsonism." (PMID 25888232, 2015). "Interestingly, recent studies have suggested direct RGS4 inhibition as a new target for Parkinson’s care." (PMID 29156651, 2017). "It has been demonstrated that RGS4 plays a significant role in various diseases, such as asthma, epilepsy, and Parkinson’s disease, and inhibition of RGS4 with their antagonists can alleviate these diseases, suggesting that RGS proteins might be the potential therapeutic target in those conditions." (PMID 35711454, 2022).